SULF1 (sulfatase 1)
Description:
Exhibits arylsulfatase activity and highly specific endoglucosamine-6-sulfatase activity. It can remove sulfate from the C-6 position of glucosamine within specific subregions of intact heparin. Diminishes HSPG (heparan sulfate proteoglycans) sulfation, inhibits signaling by heparin-dependent growth factors, diminishes proliferation, and facilitates apoptosis in response to exogenous stimulation.
Synonyms: hSulf-1; KIAA1077; SULF-1
Tractability: Antibody: UniProt places it where antibodies can reach, with high confidence; UniProt predicts a signal peptide or a membrane-spanning region; its Gene Ontology location is reachable by antibodies, with medium confidence. PROTAC: ubiquitination databases record sites on it.
Gene: Protein-coding gene on chromosome 8 (69,466,624 to 69,660,935, forward strand). Ensembl gene ENSG00000137573.
Subcellular location: Endoplasmic reticulum; Golgi apparatus, Golgi stack; Cell surface; Secreted (Extracellular sulfatase Sulf-2 secreted form)
Gene Ontology:
Molecular function: arylsulfatase activity; N-acetylglucosamine-6-sulfatase activity; calcium ion binding; sulfuric ester hydrolase activity
Biological process: heparan sulfate proteoglycan metabolic process; negative regulation of angiogenesis; negative regulation of cell migration; negative regulation of endothelial cell proliferation; negative regulation of fibroblast growth factor receptor signaling pathway; positive regulation of BMP signaling pathway; positive regulation of Wnt signaling pathway; regulation of fibroblast growth factor receptor signaling pathway; vascular endothelial growth factor receptor signaling pathway; bone development; cartilage development; chondrocyte development; embryonic skeletal system development; esophagus smooth muscle contraction; glial cell-derived neurotrophic factor receptor signaling pathway; glomerular basement membrane development; glomerular filtration; heparan sulfate proteoglycan catabolic process; innervation; kidney development; negative regulation of prostatic bud formation; positive regulation of vascular endothelial growth factor production
Cellular component: cell surface; endoplasmic reticulum; extracellular matrix; extracellular region; membrane raft; plasma membrane; Golgi apparatus; Golgi stack
Genetic constraint (gnomAD): Loss-of-function variants: 36 observed, 101.01 expected, observed/expected ratio (o/e) 0.36, 90% interval 0.27 to 0.47. The upper end of that interval is the gene's LOEUF score, 0.47, which puts it in group 2 of 6, group 1 being the genes least tolerant of losing a copy. Missense variants: 912 observed, 1,115.1 expected, observed/expected ratio (o/e) 0.82, 90% interval 0.77 to 0.86. Synonymous variants: 364 observed, 400.77 expected, observed/expected ratio (o/e) 0.91, 90% interval 0.83 to 0.99.
Homologues: Orthologues: chimpanzee SULF1 (99% identical), macaque SULF1 (97% identical), pig SULF1 (94% identical), guinea pig SULF1 (94% identical), rabbit SULF1 (94% identical), dog SULF1 (93% identical), mouse Sulf1 (93% identical), rat Sulf1 (92% identical), tropical clawed frog sulf1 (78% identical), zebrafish sulf1 (72% identical), Drosophila melanogaster Sulf1 (43% identical), Caenorhabditis elegans sul-1 (36% identical), and 6 more. Paralogues in human: SULF2 (64% identical), GNS (25% identical), ARSL (14% identical), STS (14% identical), ARSD (13% identical), ARSK (13% identical), ARSH (13% identical), ARSI (13% identical), ARSF (12% identical), ARSJ (12% identical), GALNS (12% identical), ARSG (12% identical), and 4 more.
Diseases named in the same sentence as SULF1 in open-access papers:
SULF1 is named in the same sentence as 114 diseases in open-access papers, as found by Europe PMC text mining. Sharing a sentence is not in itself a finding about the gene and the disease. The quoted sentences say what the papers report.
hepatocellular carcinoma (25 papers, 2007 to 2025). A malignant tumor that arises from hepatocytes. "Complete loss or markedly attenuated expression of SULF1 appeared in cancer cell lines derived from breast, pancreas, kidney, and hepatocellular cancers, suggesting that downregulation of SULF1 is relatively common among epithelial cancers." (PMID 36622753, 2023). "The activation of the TGFβ/SMAD transcriptional pathway underlays a novel tumor‐promoting role of SULF1 in hepatocellular carcinoma." (PMID 31612481, 2020). "In addition, an animal study confirmed that activated TGF-β pathway underlay a novel tumor-promoting role of sulfatase 1 in hepatocellular carcinoma." (PMID 27835897, 2016). "Interestingly, the insensitivity of Sulf1 as well as Sulf2 deficient cerebellar cells to staurosporine-induced cell death is similar to what has been described for hepatocellular cancer as well as head and neck squamous cell carcinoma cell lines." (PMID 26448642, 2015). "Several studies reported that SULF1 inhibited the proliferation of hepatocellular carcinoma, reduced the invasiveness in the head and neck squamous cell carcinoma and suppressed the chondrosarcoma growth." (PMID 38438372, 2024). "Some researches demonstrated that SULF1 increased the ability of migration and invasion in hepatocellular carcinoma." (PMID 38438372, 2024). "The oxidase SULF1 has been shown to modulate growth factor and cytokine signaling and to hold tumor suppressor activity in breast, pancreas, kidney, and hepatocellular cancer cell lines." (PMID 35078526, 2022). "Sulf1 is downregulated in ovarian cancer and a subset of hepatocellular carcinoma, which prevents Sulf1-mediated inactivation of receptor tyrosine kinase signalling." (PMID 33037194, 2020). "Sulf-1 expression inhibited by miR-21 in hepatocellular carcinoma led to increased cell proliferation, migration and invasion." (PMID 27626699, 2016). "Our data has shown that sulf-1 suppresses hepatocellular cancer and reduces the LNM rate of the tumor." (PMID 27626699, 2016). "We have also demonstrated that, upregulation of Sulf-1 in Hca-F cells reduced cell proliferation, migration, invasion and lymph nodes metastasis of hepatocellular carcinoma, both in vitro and in vivo." (PMID 27626699, 2016). "It had been shown earlier that hepatocellular cancer cells, expressing only low levels of Sulf1, are characterized by an insensitivity against staurosporine-induced apoptosis." (PMID 26448642, 2015). "SULF1 was found to be down-regulated in ovarian, breast, pancreatic, renal, and hepatocellular carcinoma cell lines and head and neck squamous carcinomas." (PMID 17894889, 2007). "To further understand the mechanism of Sulf-1 suppression of hepatocellular carcinoma lymphatic metastasis, we investigated it alongside with Msln gene, a cell surface glycoprotein which is known to be overexpressed in several cancers including hepatocellular carcinoma." (PMID 27626699, 2016). "Interestingly, sulfatase-1 (Sulf-1), which is a known tumor suppresser gene in various cancers including hepatocellular carcinoma has been found among the genes that have low expression in the Hca-F cell line." (PMID 27626699, 2016). "Also inhibition of Sulf-1 in hepatocellular carcinoma facilitated the formation of Epithelial Mesenchymal Transition (EMT) and this increased the chance of distance metastasis by activating AKT/ERK pathways." (PMID 27626699, 2016). "In fact, the expression of Sulf1 mediated by adenovirus in liver carcinoma cells downregulates the activity of AKT and ERK signaling pathways, and inhibits HCC cell migration and proliferation, which makes it a candidate anti-tumor factor for cancer gene therapy." (PMID 25105093, 2014). "Thus, for example, SULF1 is upregulated in significant subsets of breast cancer, pancreatic cancer lung adenocarcinoma and hepatocellular carcinoma, while SULF2 is upregulated in multiple myeloma, breast cancer and CNS cancers." (PMID 17460759, 2007).
hepatocellular carcinoma (continued). "Earlier reports have pointed out the tumor suppressive role of SULF-1 in hepatocellular carcinoma (HCC)." (PMID 36359323, 2022). "In this respect, SULF1 displayed tumor suppressor function in hepatocellular carcinoma (HCC), ovarian cancer, kidney cancer and multiple myeloma." (PMID 28525382, 2017). "SULF1 has been shown to exhibit tumor suppressive properties in hepatocellular carcinomas (HCC), as well as breast and ovarian cancers, potentially acting by reducing growth factor binding and signaling in expressing cells." (PMID 28672878, 2017). "In conclusion, our findings show that Sulf-1 is an important tumor suppressor gene in hepatocellular carcinoma (HCC), and its overexpression downregulates Msln and results in a decrease in HCC cell proliferation, migration, invasion, and lymphatic metastasis." (PMID 27626699, 2016). "In hepatocellular carcinoma (HCC), SULF1 promotes TGFB-induced gene expression and EMT transition." (PMID 41373732, 2025). "Previous study reported that SULF1 activated the TGF-β/SMAD pathway by binding to TGFBR3 and decreasing the interaction between TGF‐β1 and TGFBR3 in hepatocellular carcinoma." (PMID 38438372, 2024). "Evidence suggests that overexpression of SULF1 is related to expression of EMT genes and can promote EMT in human hepatocellular carcinoma." (PMID 34107956, 2021). "In this current study we have investigated the role of Sulf-1 in tumorigenesis and the role it plays in LNM of hepatocellular cancer." (PMID 27626699, 2016). "Similarly, miR-21 inhibits its targets-PTEN and sulfatase-1 (hSulf-1) expression in hepatocellular carcinoma (HCC) cells and finally enhances HCC cell proliferation and movement." (PMID 26690371, 2015). "In a highly metastatic hepatocellular carcinoma cell line SMMC-7721, Sulf-1 was reported to have inhibited complex formation between hepatocyte growth factor ligand and tyrosine kinase receptor c-met and this further inhibited the activation of ERK, PI3K/AKT pathway." (PMID 27626699, 2016). "However, only few have reported the role of Sulf-1 in liver cancer metastasis, and not many of them attempted to directly address LNM of hepatocellular carcinoma." (PMID 27626699, 2016).
gastric cancer (22 papers, 2007 to 2025). A primary or metastatic malignant neoplasm involving the stomach. "Functionally, cancer-associated fibroblasts-derived SULF1 served as a oncogenic molecule which facilitated gastric cancer cells metastasis and CDDP resistance." (PMID 38438372, 2024). "Mechanistically, SULF1 regulated the communication between gastric cancer cells and cancer-associated fibroblasts in tumor microenvironment as a signaling molecule." (PMID 38438372, 2024). "The objective of this study was to examine the role and underlying molecular mechanisms of SULF1 in the context of gastric cancer." (PMID 38438372, 2024). "We found that the expression of SULF1 was increased in gastric cancer, especially in cancer-associated fibroblasts." (PMID 38438372, 2024). "Overall, we illustrated that SULF1 was highly expressed in gastric cancer and was associated with advance clinicopathological characteristics and poor prognosis." (PMID 38438372, 2024). "In gastric cancer patients, overexpression of miR-516-3p is associated with decreased SULF1 expression and increased survival." (PMID 28672878, 2017). "Overexpression of Sulf-2 has been shown to inhibit growth of myeloma tumors and breast cancer xenografts, and Sulf-1 has been associated with poor prognosis in gastric cancer and lung adenocarcinoma." (PMID 24459635, 2014). "Recent studies showed that the increased expression of SULF1 increases metastasis and cisplatin resistance in gastric cancer." (PMID 39682235, 2024). "Cancer-associated fibroblasts-secreted SULF1 interfered with the interaction between TGF-β1 and TGFBR3 by combining with TGFBR3 on gastric cancer cell membrane, subsequently activated TGF-β signaling pathway." (PMID 38438372, 2024). "The overexpression of SULF1 was found to be significantly correlated with unfavorable prognosis among individuals diagnosed with gastric cancer." (PMID 38438372, 2024). "In conclusion, our findings have presented novel approaches for potential treatment and prognosis prediction in individuals diagnosed with gastric cancer through the targeting of the CAFs-SULF1-TGFBR3-TGF-β1 signaling axis." (PMID 38438372, 2024). "We extracted primary NFs, CAFs and GC cells from human gastric cancer and paracancerous tissues to verify the expression of SULF1." (PMID 38438372, 2024). "Several experimental studies reported SULF1 as a tumor suppressor effector and its down-regulation levels related to several cancers such as pancreatic, ovarian and gastric cancer." (PMID 34107956, 2021). "In fact, SULF1 has displayed tumor-promoting activity in pancreatic, urothelial, and gastric cancers, which further highlights the complex outcomes of SULF1 activity in vivo." (PMID 32413029, 2020). "Sonic Hedgehog (shh) signaling was enhanced during embryonic development and axonal guidance but repressed in gastric cancer by SULF1." (PMID 28525382, 2017). "Consistently, Sulf-1 is reported to suppress the growth and cell proliferation of gastric cancer cell line MKN28 by inhibiting Hedgehog signaling that results from the removal of the 6-O-sulfate group from HSPGs." (PMID 27626699, 2016). "In human gastric cancer, Sulf-1 was reported to inhibit hedgehog signaling involved in Epithelial Mesenchymal transition (EMT) and at the same time it down regulated metastasis associated genes such as GLI1, PTCH1/2, HHIP, c-myc, CCND1, FOXM1 and bcl2." (PMID 27626699, 2016). "In gastric cancer cells, expression of Sulf1 significantly suppressed cellular proliferation possibly through abrogating the Hedgehog signaling pathway." (PMID 25105093, 2014). "Higher expression of Sulf1 and Sulf2 compared to normal mucosa has been reported in gastric cancer, with the expression of Sulf1 significantly correlated with higher recurrence rates and worse overall survival in patients." (PMID 25105093, 2014). "In one study, only 13 early-stage breast and gastric cancers, most of which were stage I, were analyzed by semi-quantitative RT-PCR for SULF1 expression." (PMID 24124496, 2013).
gastric cancer (continued). "For instance, SULF1 secreted by CAFs binds to TGFBR3 on the surface of gastric cancer cells, alters its interaction with TGF-β1, and subsequently facilitates the activation of the TGF-β signaling pathway, thereby promoting metastasis and resistance to cisplatin." (PMID 40843362, 2025). "The findings suggest that SULF1 could serve as a promising target for inhibiting the progression of gastric cancer generated by CAFs." (PMID 38438372, 2024). "Likewise, the hypermethylation in HS 6-O-endosulfatase Sulf-1 promoter region downregulates its expression in gastric cancer cell lines and tissue samples, and the decreased levels of HS 6-O-endosulfatase associate with gastric cancer progression." (PMID 33494442, 2021). "Yoshifumi Takei et al14 demonstrated that the expression of miR‐516a‐3p in 44As3 cells (highly metastatic gastric cancer cells) was lower than that in HSC‐44PE cells (parental cells isolated from patients), and sulfatase 1 was a direct target of the miR‐516a‐3p in gastric cancer." (PMID 31273950, 2019). "Finally, Sulf-1 has been shown to either enhance or repress Sonic Hedgehog (Shh) signaling during neuronal development or in gastric cancer, respectively." (PMID 24459635, 2014). "SULF1 has been shown to be a potential biomarker for gastric cancer which can be induced by TGF-β1." (PMID 23251436, 2012). "To summarize, this present study indicated that CAFs within gastric cancers promoted metastasis and CDDP resistance through the secretion of SULF1." (PMID 38438372, 2024). "We have also observed epigenetic upregulations of SULF1 and SEMA3C earlier found upregulated in gastric cancer and breast cancer, respectively." (PMID 31796082, 2019). "Human Sulf1 is silenced in the gastric cancer cell line MKN28, and when Sulf1 expression is restored, the oncogenic phenotype is reduced along with a reduction in canonical Wnt signalling." (PMID 25681501, 2015). "In another study, the expression of both SULF1 and SULF2 mRNA was determined by real-time RT-PCR for a large cohort of gastric cancer tissues, finding that SULFs were expressed at higher levels in gastric cancer as compared with normal tissues." (PMID 24124496, 2013). "However, upregulation of both SULF1 and SULF2 has been shown to be a poor prognostic indicator for gastric cancer patients." (PMID 28672878, 2017). "The topmost molecular network in the intestinal subtype on IPA network analysis showed increased expression of SULF1, HGF, SPARC, SERPINH1, and IGFBP7, which have been shown to contribute to the growth and survival of tumor cells, tumor invasion, metastasis, and poor survival in gastric cancer." (PMID 34885041, 2021). "Limited studies indicate that INTS8 contains mutations in peripheral T cell lymphoma compared with non-malignant samples from 12 patients, and a combination of INTS8 with SULF1, ATP6V1C1, and GPR172A can be used to discriminate gastric carcinomas from adjacent noncancerous tissues." (PMID 27567667, 2016).